BAMBI (BMP and activin membrane bound inhibitor)
Diseases named in the same sentence as BAMBI in open-access papers (continued):
Sharing a sentence is not in itself a finding about the gene and the disease.
tumor (continued). "We measured BAMBI expression in tumor-infiltrating MDSCs from Lyz2creRelafl/fl mice and found Rela KO can increase BAMBI expression and rescue the reduction of BAMBI." (PMID 38099498, 2023). "Evidence for a tumor-protective function of BAMBI was obtained by a study showing that C-terminal truncated HBV X, which contributes to carcinogenesis in HBV infection, downregulated BAMBI." (PMID 36834884, 2023). "BAMBI mRNA expression was also upregulated in the HCC tissues of 20 patients when compared to the respective non-tumor tissues." (PMID 36834884, 2023). "Here, BAMBI protein was strongly suppressed in HCC tissues compared to tumor-adjacent tissues of the four different patients analyzed." (PMID 36834884, 2023). "Further evidence for a tumor-promoting role of BAMBI came from the high expression of BAMBI in tumors with overexpression of the hepatic stem cell marker, epithelial cell adhesion molecule (EpCAM)." (PMID 36834884, 2023). "We further confirmed the BAMBI reduction in tumor-infiltrating MDSCs from WT+IR versus WT mice and the BAMBI induction in MDSCs from Ythdf2-cKO versus WT mice at both mRNA and protein levels." (PMID 38099498, 2023). "BAMBI suppresses the tumor-infiltrating capacity and suppression function of MDSCs via inhibiting TGF-β signaling." (PMID 38099498, 2023). "Consistent with promotion of tumor aggression, patients with high BAMBI expression had poorer prognosis than those with low BAMBI expression as reflect by overall survival (hazard ratio 1.9, 95% confidence interval, p = 0.011)." (PMID 36109807, 2022). "Our findings suggest that BAMBI promote MM cell proliferation and tumor aggression by acting downstream of CTGF." (PMID 36109807, 2022). "The reduction in MM cell proliferation by BAMBI knockdown suggests that BAMBI normally regulate cell proliferation, thereby increasing tumor aggression." (PMID 36109807, 2022). "In this way we identify a number of tumor-specific dependencies, including a previously uncharacterized dependency on the TGFβ pseudo-receptor BAMBI." (PMID 32584896, 2020). "Taken together, these findings suggested that exosomal miR-17-5p promoted tumor angiogenesis by downregulating BAMBI via AKT/VEGF-A signaling." (PMID 31777597, 2019). "Our research showed that miR-17-5p, expressed and secreted by NPC cells, plays a role in promoting tumor progression and angiogenesis by inhibiting the downstream target BAMBI." (PMID 31777597, 2019). "Nude mice injected with GFP-BAMBI expressing cells formed fewer nodules and had a reduced tumor burden in the lungs compared to GFP controls suggesting that BAMBI is a potent inhibitor of TGF-β1-mediated EMT and invasion in vitro and in vivo." (PMID 29799477, 2018). "In contrast, ctHBx seems to be more oncogenic than HBx through the inhibition of tumor-suppressive β-catenin/BAMBI signaling." (PMID 27909336, 2016). "This newly described role for BAMBI in regulating endothelial function has potential implications for understanding and treating vascular disease and tumor neo-angiogenesis." (PMID 22761782, 2012). "Based on these observations it has been proposed that during tumorigenesis, BAMBI upregulation allows tumor cells to escape growth arrest by TGFβ, and to activate growth and increase tumor cell motility and invasion." (PMID 20886049, 2010). "Immunohistological localizations for BAMBI have so far only been reported for various tumors, where the staining was assigned to the tumor cells." (PMID 20886049, 2010). "With the exception of various tumor tissues, few data are available on the organ and cell-specific expression of BAMBI." (PMID 20886049, 2010). "Based on these findings, the authors proposed that BAMBI overexpression during radiotherapy could improve local tumor control by counteracting extrinsic radiation resistance." (PMID 40332515, 2025).
tumor (continued). "BAMBI acts as an inhibitor of the transforming growth factor-β type 1 receptors, playing a promoting role in advanced tumors and an inhibitory role during early tumor development." (PMID 41487817, 2025). "In particular, the relationships of BAMBI with tumor immunity and glycolipid metabolism in HCC remain unclear." (PMID 39684424, 2024). "Importantly, BAMBI suppresses the tumor-infiltrating capacity and suppressive function of MDSCs by inhibiting TGF-β signaling." (PMID 38099498, 2023). "BAMBI thus protects from fibrosis but may also regulate anti-tumor immune responses and tumor growth." (PMID 36834884, 2023). "With overexpression of BAMBI, these changes were reversed, allowing improved tumor control." (PMID 38099499, 2023). "BAMBI was shown to exert tumor-promoting and cancer-protective functions." (PMID 36834884, 2023). "Considering that BAMBI is expressed at various levels in immune cells, we speculate that BAMBI may affect their function and thereby affect host tumor immune response." (PMID 38099498, 2023). "Interestingly, the last cell type reducing survival represented a BAMBI-expressing tumour cluster with a clear cell-like phenotype." (PMID 34238352, 2021). "In this respect, HGSTOC tumours overexpressing BAMBI could share features with clear cell ovarian tumours." (PMID 34238352, 2021). "However, the growth of SH-J1 cells transduced with Ad-BAMBI was markedly suppressed, suggesting that BAMBI overexpression leads to significant inhibition of tumor growth in vivo." (PMID 27909336, 2016). "Taken together, ctHBx may have a more oncogenic role than HBx through its inhibition of tumor-suppressive β-catenin/BAMBI signaling." (PMID 27909336, 2016). "Thus our data suggest that HBx stimulates Wnt/β-catenin signaling, which is followed by tumor-suppressive β-catenin/BAMBI signaling." (PMID 27909336, 2016). "As BAMBI is co-expressed with members of the TGFβ family during development and in cancer, it was proposed, that BAMBI may play a role in development and in tumor growth and metastasis." (PMID 22761782, 2012). "The endothelial localization of BAMBI may indicate novel, yet to be defined, functions of this modulator in the vascular endothelium in health and disease, and potentially even in tumor progression." (PMID 20886049, 2010). "In the tumors the expression of BAMBI seemed to correlate with tumor growth and metastasis." (PMID 20886049, 2010). "BAMBI has been proposed to play a role in TGFβ and Wnt signaling, and as such may markedly influence fibrosis and tumor progression." (PMID 20886049, 2010). "Thus, in cancer cells, high BAMBI expression is supposed to enhance tumor growth." (PMID 36834884, 2023). "Also, exosomal miR-17-5p released from cancer cells may promote tumor angiogenesis by directly targeting BAMBI." (PMID 31777597, 2019). "Finally, we investigated the tumor-suppressive role of BAMBI in hepato-oncogenesis." (PMID 27909336, 2016). "Therefore, downregulation of both β-catenin and TGF-β1 signaling by BAMBI might contribute to tumor suppression in mice xenotransplanted with HepG2 or SH-J1 cells." (PMID 27909336, 2016). "Mechanistically, HBx‐mediated down‐regulation of miR‐19a‐3p activated the BAMBI/Wnt signalling pathway, thereby enhancing TGF‐β1 secretion and suppressing the anti‐tumour activity of CD4+ T cells." (PMID 41492119, 2026). "Clinically, progressive or deceased DLBCL patients exhibited markedly higher levels of BAMBI and TGFB1 in tumour tissues compared with complete responders." (PMID 41492119, 2026). "Consistent with the dual role of TGF-β in HCC, BAMBI has also been shown to have dual roles in HCC, demonstrating both tumor-promoting and tumor-protective effects." (PMID 40260391, 2025). "BAMBI, a known antagonist of the TGF-β pathway, typically suppresses epithelial–mesenchymal transition (EMT) and tumor invasion." (PMID 41395597, 2025).
tumor (continued). "A previous study from our group analyzed tumor-adjacent and HCC expression of BAMBI by immunoblot and observed low BAMBI protein in the tumors." (PMID 39457709, 2024). "BAMBI protein levels in non-tumor and HCC tissue of patients with HCV were low compared to HBV infection, showing that disease etiology has to be considered when studying the role of BAMBI in fibrogenesis and carcinogenesis." (PMID 39457709, 2024). "BAMBI blocks TGF-β activity, which normally induces cell growth arrest, and in cancer cells, high BAMBI expression is thought to promote tumor growth." (PMID 39457709, 2024). "BAMBI protein analyzed by immunohistochemistry of HCC tissues was 1.6 ± 0.7 and of non-tumor tissues was 1.5 ± 0.6, and was similar (p = 0.164) between these tissues." (PMID 39457709, 2024). "BAMBI mRNA was also induced in Hep3B and Huh7 cells by microRNA-HCC2, which is overexpressed in HCC tissues compared to non-tumor tissues." (PMID 36834884, 2023). "Compatible with low BAMBI protein in HCC tissues, tumor-protective roles of BAMBI have also been described." (PMID 36834884, 2023). "Downregulation of BAMBI was observed to promote TGF-β-induced EMT, migration and invasion of NSCLCs in vitro, along with increased tumor burdens and tumor growth in vivo." (PMID 35270630, 2022). "Thus the induction of BAMBI may function in part as a tumor-suppressor mechanism in HCC." (PMID 27909336, 2016). "STK3 and BAMBI qRT-PCR results validated significant overexpression of the genes in tumour compared to patient-matched, non-tumour tissues (n = seven matched pairs of samples, p ≤ 0.05 for both genes)." (PMID 40566602, 2025). "Moreover, BAMBI was found to have dual roles in HCC, demonstrating both tumor-promoting and tumor-protective effects." (PMID 40260391, 2025). "BAMBI acts as an oncogene in HCC and likely participates in tumor immunity modulation." (PMID 39684424, 2024). "BAMBI protein in the non-tumor tissues was not correlated with fibrosis and inflammation scores (p > 0.05)." (PMID 39457709, 2024). "BAMBI protein levels in tumor and non-tumor tissues were not related to inflammation and fibrosis grade." (PMID 39457709, 2024). "In HBV-positive and HBV-negative patients, the tumor to non-tumor BAMBI mRNA ratio was 1.5 and 1.4, respectively, indicating almost similar BAMBI mRNA expression in the non-tumor tissues and the tumors." (PMID 39457709, 2024). "In HCC tissues of HBV-positive and HBV-negative patients, the tumor to non-tumor BAMBI mRNA ratio was 1.5 and 1.4 (p > 0.05), respectively, showing that BAMBI expression did not greatly differ between the tumor and the non-tumor tissues." (PMID 36834884, 2023). "One of these analyses included five HCC cases, and BAMBI expression was increased in the tumors of three cases and comparable between tumor and non-tumor tissues of two cases." (PMID 36834884, 2023). "Interestingly, expression of the marker gene BAMBI, a TGF-β pseudoreceptor involved in EMT and constitutive IL2/STAT5 signalling, has previously been correlated with tumour growth, tumour invasion and carboplatin resistance in HGSTOC." (PMID 34238352, 2021). "This showed that BAMBI protein was similar in non-tumor and tumor tissues." (PMID 39457709, 2024). "BAMBI plays an oncogenic role in HCC and may modulate tumor immunity." (PMID 39684424, 2024). "However the basic information on cell type-specific expression of BAMBI in mammalian organs is lacking, as only whole organ or tumor mRNA levels have been reported." (PMID 22761782, 2012). "Therefore, we further confirmed whether the upregulated BAMBI, SLC26A9, SGPP2, and TMC8 genes could be used as a gene signature for EBVaCAs by determining the expression levels of these four genes in cell lines and tumor tissues by qRT-PCR." (PMID 35008199, 2021). "A sex-specific analysis showed that the BAMBI protein levels of female HCC tissues were not related to T stage, lymph node invasion, vessel invasion, grading, tumor size, or UICC score." (PMID 39457709, 2024).
tumor (continued). "In 53 public datasets, BAMBI mRNA was induced in the HCC tissues of 31 cohorts and was similar between the tumor and non-tumor tissues of 22 cohorts." (PMID 39457709, 2024). "BAMBI protein levels of male HCC tissues were not related to T stage, lymph node invasion, vessel invasion, grading, tumor size, or UICC score." (PMID 39457709, 2024). "Similar levels of BAMBI protein in HCC and non-tumor liver tissues are in contrast to a study from China, where tumor BAMBI protein levels were found to be elevated." (PMID 39457709, 2024). "In contrast, BAMBI and TNFRSF19 positive cells from primary tumor sections did not express or only minimally expressed MKI67." (PMID 33898197, 2021). "Paired tumor and non-tumor tissues from patients with HBV, which were not available for our study, are needed to clarify whether upregulation of the BAMBI protein in HCC is more common in these patients." (PMID 39457709, 2024). "Similarly, the expression of SLC26A9 and TMC8, but not BAMBI or SGPP2, was significantly upregulated in EBV-positive tumor tissues compared with that in EBV-negative tumor tissues." (PMID 35008199, 2021). "However, SLC26A9 and TMC8, but not BAMBI and SGPP2, were significantly upregulated in EBV-positive tumor tissues compared to EBV-negative tumor tissues." (PMID 35008199, 2021). "For patients undergoing tumor-directed RT, it appears that the negative consequences of TGF-β may be at least partly due to RT-induced reduction of the TGF-β pseudoreceptor, bone morphogenetic protein and activin membrane-bound inhibitor (BAMBI)." (PMID 38099499, 2023).
cancer (20 papers, 2012 to 2025). A tumor composed of atypical neoplastic, often pleomorphic cells that invade other tissues. "Overexpression of BAMBI inhibited the TGF-β-driven differentiation of bone marrow-derived mesenchymal stem cells into cancer-associated fibroblasts." (PMID 39457709, 2024). "High BAMBI expression bears a risk of promoting the development of tumors, but current data suggest that the cancer-protective effects predominate." (PMID 36834884, 2023). "Our findings uncover a mechanism by which BAMBI expression in myeloid cells can suppress pathways that cause extrinsic radioresistance and unveil a potential therapeutic strategy for cancer treatment." (PMID 38099498, 2023). "Overexpression of BAMBI inhibited TGF-β-induced differentiation of bone marrow-derived mesenchymal stem cells to cancer-associated fibroblasts." (PMID 36834884, 2023). "While BAMBI has been implicated in cancer progression, these tumorigenic functions appear to be highly context-dependent." (PMID 36109807, 2022). "Several cancer types appear to express elevated levels of BAMBI and these types are associate with poor prognosis." (PMID 36109807, 2022). "ID1, ID2 and RUNX2 were also shown to conduce to cancer cell invasiveness, and BAMBI is a BMP target gene implicated in CRC metastasis." (PMID 32326239, 2020). "These mechanistic actions of BAMBI explain a large set of observations where misregulation of BAMBI expression associates with a variety of human diseases, including cancer, chronic inflammation, tissue fibrosis and cardiovascular disease." (PMID 32210029, 2020). "A few genes associated with disease were identified, including BMP and activin membrane-bound inhibitor (BAMBI), which has been associated with various pathologies, including cancer, and also poorly studied genes of potential interest like GRB2-binding adaptor protein, transmembrane (GAPT)." (PMID 25565328, 2015). "BAMBI expression is increased in many carcinomas, contributing to the proliferation and metastasis of neoplastic cells due to escape from TGF-β growth arrest (Figure A2B)." (PMID 40566602, 2025). "Our analysis of expression profiles and prognostic values demonstrated the potential roles of BAMBI in the development and progression of various human cancers." (PMID 39684424, 2024). "Since BAMBI is linked to the development and progression of various human cancers, we explored the expression profiles of BAMBI in 24 human cancer types." (PMID 39684424, 2024). "Bone morphogenetic protein and activin membrane-bound inhibitor (BAMBI) reportedly contributes to the development and progression of various human cancers." (PMID 39684424, 2024). "In this study, we analyzed the expression profiles of BAMBI, along with its contributions to pathological findings, metastasis characteristics, and prognosis in multiple human cancers." (PMID 39684424, 2024). "We constructed a multi-cancer fibroblast atlas, in which fibroblasts were classified into six clusters: BAMBI+ FBs, CLDN1+ FBs, COL11A1+ FBs, CXCL14+ FBs, DPT+ FBs and RGS5+ FBs." (PMID 36744260, 2023). "Together, our in silico observations suggest that elevated BAMBI levels correlate with better survival and antitumor immunity among cancer patients." (PMID 38099498, 2023). "Bone morphogenetic protein and activin membrane-bound inhibitor (BAMBI) antagonizes TGF-β signaling and is implicated in cancer progression." (PMID 38099498, 2023). "The most important observations are the hypomethylation of the CLEC12B and BAMBI genes, which are responsible for inhibiting the proliferation of cancer cells." (PMID 38201971, 2023). "We analyzed transcriptomic data sets of cancer patients to examine the potential relationship of BAMBI to cancer patient survival by leveraging the Kaplan-Meier plotter website." (PMID 38099498, 2023). "Despite this, our findings reveal detailed insights into therapeutically targeting BAMBI for the treatment of cancer." (PMID 38099498, 2023).